OR52H1 (olfactory receptor family 52 subfamily H member 1)
Description:
Odorant receptor.
Synonyms: OR11-41; OR11-45
Tractability: Antibody: UniProt predicts a signal peptide or a membrane-spanning region; its Gene Ontology location is reachable by antibodies, with medium confidence. PROTAC: ubiquitination databases record sites on it.
Gene: Protein-coding gene on chromosome 11 (5,544,489 to 5,548,540, reverse strand). Ensembl gene ENSG00000181616.
Subcellular location: Membrane
Pathways (Reactome):
Sensory Perception: Expression and translocation of olfactory receptors
Gene Ontology:
Molecular function: olfactory receptor activity; G protein-coupled receptor activity
Biological process: detection of chemical stimulus involved in sensory perception of smell; G protein-coupled receptor signaling pathway; nervous system process
Cellular component: plasma membrane; membrane
Genetic constraint (gnomAD): Loss-of-function variants: 2 observed, 1.21 expected, observed/expected ratio (o/e) 1.66, 90% interval 0.48 to 1.93. That is too few expected variants to judge how well the gene tolerates losing a copy. Missense variants: 383 observed, 418.07 expected, observed/expected ratio (o/e) 0.92, 90% interval 0.84 to 1. Synonymous variants: 148 observed, 146.49 expected, observed/expected ratio (o/e) 1.01, 90% interval 0.88 to 1.16.
Homologues: Orthologues: chimpanzee OR52H1 (95% identical), dog OR52H1B (89% identical), pig OR52H1 (89% identical), mouse Or52h1 (89% identical), dog OR52H1 (89% identical), rat Or52h1 (89% identical), tropical clawed frog or52al1 (51% identical), tropical clawed frog or52d1 (50% identical). Paralogues in human: OR52B2 (61% identical), OR52B6 (55% identical), OR52E8 (55% identical), OR52E4 (55% identical), OR52D1 (54% identical), OR52E2 (53% identical), OR52B4 (53% identical), OR52E5 (52% identical), OR52E6 (52% identical), OR52J3 (51% identical), OR52R1 (50% identical), OR52N4 (50% identical), and 39 more.